CTLA4 (cytotoxic T-lymphocyte associated protein 4)
Diseases named in the same sentence as CTLA4 in open-access papers (continued):
Sharing a sentence is not in itself a finding about the gene and the disease.
viral infection (continued). "Other immune checkpoints, such as cytotoxic T-lymphocyte associated protein 4 (CTLA4), lymphocyte activating 3 (LAG3) and indoleamine 2,3-dioxygenase 1 (IDO1) have been also studied in immunosuppressive viral diseases such as PMWS and CSF." (PMID 34046040, 2021). "Studies have shown that blockade of CTLA-4 promoted the expansion of germinal center B-cells in viral infection or immunization with model antigens." (PMID 32517277, 2020). "Chronic viral infection is associated with T cell exhaustion manifested by sustained expression of inhibitory receptors such as PD-1, 2B4 (CD244), CTLA4, LAG3, TIM3, CD16022." (PMID 32020034, 2020). "Blocking of PD-1 or CTLA-4 signaling has shown clinical benefit not only in cancer and viral infections but also in ex vivo parasitic infection studies as well." (PMID 29915577, 2018). "Only few data are available on virus replication and virus infection in patients receiving CTLA-4-immunoglobulins." (PMID 27088031, 2016). "Many researchers have attempted to control chronic virus infection using immunotherapeutic interventions such as blockade of the inhibitory receptors PD–1 and CTLA–4, administration of type I IFN, and regulation of microRNAs." (PMID 26452143, 2015). "To determine which mechanism is contributing to Treg-mediated decrease of viral infection, we analyzed in parallel the effect of combined CTLA-4 and cAMP blockade on HIV replication, actin polymerization in the IS, DC maturation, and Tcon activation." (PMID 24847325, 2014). "The CTLA4 haplotypes CGTAG and CGCAG were partially associated with the development of viral infection in Chinese kidney transplant recipients." (PMID 24015180, 2013). "In conclusion, the CTLA4 haplotypes CGTAG and CGCAG were partially associated with the development of viral infection in Chinese kidney transplant recipients." (PMID 24015180, 2013). "Interestingly, this work demonstrated that the expression level of CTLA-4 exhaustion marker was elevated during acute viral infection." (PMID 36311780, 2022). "Similarly, exhaustion markers Lag3, Tigit, and Ctla4 were uniformly increased in all CD4+ T cell subsets responding to chronic viral infection." (PMID 36255051, 2022). "A role for OX40L and CTLA4 and CD11c in cancer immunology and viral infections has been reported." (PMID 36230846, 2022). "Our in silico analysis revealed that miR-148b might regulate TGF-ꞵ and CTLA4 signaling pathways, both of which were the important components of cellular immunity against viral infections." (PMID 35401158, 2021). "This study suggests that viral infection may recruit immune effector cells and that it may activate PD-1 and CTLA-4 immunosuppressive pathways." (PMID 30911684, 2019). "Our work reveals that viral infection may recruit immune effector cells, and upregulate PD-1 and CTLA-4 immunosuppressive pathways." (PMID 30911684, 2019). "In contrast to IKAROS defects but similar to cytotoxic T lymphocyte–associated protein 4 (CTLA4) haploinsufficiency, we observed that NFKB1 haploinsufficiency can also result in chronic and severe viral disease, as noted for cytomegalovirus and JC virus infections in 3 of our patients." (PMID 29477724, 2018). "Viral infections will accelerate antiviral immune reactions of CTLA-4, which induce β-cell death." (PMID 29082260, 2017). "Therefore, the sustained expression of PD-1 and CTLA-4 is attributed to the chronicity of viral infection." (PMID 28703774, 2017). "However, in some viral infections, targeting CTLA-4 has led to increased viral production and a reduction in anti-viral therapy." (PMID 28981470, 2017). "It has been reported that CTLA-4 signaling may result in high CCR5 expression and enhanced susceptibility to viral infection." (PMID 26452480, 2015). "HLA-DR and CTLA4 may serve as upregulation markers in the recovery phase and may have a role in checking and re-balancing the lymphocytes once the viral infection is under control." (PMID 24658451, 2014).
viral infection (continued). "The allele distribution of CTLA4 polymorphisms in patients with viral infection and non-viral infection." (PMID 24015180, 2013). "Therefore, the outcomes of the viral infection vary according to the vigor of the immune response, a process that is regulated by several molecules, including the cell surface receptor CTLA-4, which is consistent with its emerging role in the T regulatory cells in the pathogenesis of the disease." (PMID 38180994, 2024). "Interestingly, CTLA-4 may play different roles in various signaling pathways in viral infections, such as lymphocytic choriomeningitis virus, human immunodeficiency virus and hepatitis C virus." (PMID 24337678, 2014). "Positive expression of iRs such as PD1, CTLA-4, TIM3, LAG-3, 2B4, CD160, and BTLA has been directly linked to reduced cytokine production by T cells from cancer patients (including reports from our group) or in the chronic LCMV mouse model of “T cell exhaustion” and other viral infections." (PMID 24391639, 2013). "Thus, PD-1 may play a more universal role in antiviral T cell exhaustion whereas the effect of CTLA-4 may differ between viral infections, T cell subsets and even anatomical locations." (PMID 19247441, 2009). "In Class1, the viral infection pathways (e.g., HSV-1, EBV) and antigen presentation (e.g., HLA-DRB1/DQB1/C, CD74, CTLA4, GZMB, PRF1) were primarily enriched." (PMID 41394852, 2025). "Several research papers suggest that expression of co-inhibitory molecules such as PDCD1 (PD-1), HAVCR2 (Tim-3), CTLA4, and LAG3 correlates with the activated and more differentiated state of CD8+ T cells in viral infection." (PMID 37409113, 2023). "Having correlated gene-specific viral integration with elevated PD-L1 and PD-L2 expression in HPV-positive HNSC, we next correlated any viral infection with PD-L1, PD-L2, PD-1, CD80, CD86, CTLA-4, Tim-3, LAG3, and 4-1BB expressions." (PMID 30911684, 2019). "Although exhaustion of CD4+ and CD8+ T cells have been described by many clinical studies during chronic viral infection, we found that there were more CD4+ T cells expressing PD1 and CTLA4 compared to CD8+ T cells in this model." (PMID 28886065, 2017). "In the downregulated clusters, a vast quantity of inflammatory/immune pathways are present (related to viral infection, IFN targets, CTLA4 pathway, Graft-versus host disease, etc.)." (PMID 27805902, 2016). "This is different from observations in chronic and acute viral diseases where it has been shown consistently that viral load correlates with PD1 and CTLA4 expression on T cells." (PMID 27802341, 2016). "While CTLA4 expression was not affected by oncolytic viral infection, PD1 resulted highly upregulated in tumors after unarmed R-LM113 treatment." (PMID 38839891, 2024). "By contrast, CTLA4 is another ligand for CD80/CD86 which presents even a higher avidity than CD28, acting as a critical inhibitor of T-cell activation and proliferation in several viral infections." (PMID 36713151, 2022). "However, patients with simultaneous bacterial and viral infections at admission presented with increased PD-1 expressions on CD4 + and CD8 + T cells, higher PD-L1 expression on CD8 + T cells and CTLA4 expression on CD4 + T cells." (PMID 35246776, 2022). "In this study, the upregulated expression of CTLA-4, LAG-3, 2B4, and TIGIT were observed in CD8+ T cells and CD4+ T cells of mice infected with FMDV, which would inhibit T-cell proliferation and promote T-cell apoptosis during virus infections." (PMID 34960627, 2021). "The distribution of haplotypes in 5 locus of CTLA-4 between viral infection and non-viral infection." (PMID 24015180, 2013). "Cluster 5 is related to immune tolerance to viral infections, and its subclusters 5–14 are related to TIGIT and CD155, which are considered to be the third molecules for immune checkpoints following PD-1/PDL-1 and CTLA4/CD80/86, whose inhibitors have already been used in pharmaceuticals." (PMID 34811710, 2022).
viral infection (continued). "Second, oncolytic viruses infection itself could induce the up-regulation of CTLA-4 or PD-L1 through activation of IFN-γ producing cytotoxic CD8 T cells, thereby allowing antibodies targeting CTLA-4 and PD-1/PD-L1 pathway to reach their maximum therapeutic potential." (PMID 26580645, 2015).
hypothyroidism (65 papers, 2012 to 2025). Abnormally low levels of thyroid hormone. "Eleven patients developed hypothyroidism subsequent to thyrotoxicosis, 4 of which were associated with PD-1 and CTLA-4 inhibitors." (PMID 40388765, 2025). "Female sex and combination therapy with anti-PD-1 and anti-CTLA-4 were associated with hypothyroidism, which is consistent with the 2 large previous studies." (PMID 40503677, 2025). "The relationship between checkpoint inhibition and hypothyroidism in clinical practice, alongside observing individual associations to CTLA4 and LAG3, encouraged us to look further at the role of genetic predisposition." (PMID 39041034, 2024). "For example, the occurrence of multiple variants for CTLA4 gene in the Taiwan cohort increased the risk for hypothyroidism (odds ratio (OR) 1.4–1.9)." (PMID 38919955, 2024). "In this study, 22 and 17 genes in the hypothyroidism and hyperthyroidism group, respectively, associated with anti-CTLA-4 therapy were identified for functional analysis by GO and KEGG enrichment." (PMID 32500465, 2020). "Cytotoxic T-lymphocyte-associated protein 4 (CTLA4) is another gene implicated in this condition, as demonstrated by a study that used reverse transcription polymerase chain reaction to analyze genetic markers in patients with hypothyroidism." (PMID 39726471, 2024). "The most frequently reported general symptoms are fatigue and weakness, which may be a direct result of anti-PD-1/anti-CTLA-4 therapy, but may also be a symptom of endocrinopathy, e.g., hypothyroidism, or even a sign of progression of the underlying disease." (PMID 34236546, 2021). "However, in contrast, with the endocrine system, the use of anti-CTLA-4 or anti-PD-1 immunotherapy is reported to have a greater potential to cause endocrine issues (such as hypothyroidism, hyperthyroidism, thyroiditis, and adrenal insufficiency) in other cancers." (PMID 41237182, 2025). "The incidence of hypothyroidism was 19.6% in the combination therapy, 9.9% in anti-PD-1 therapy, 8.7% in anti-PD-L1 therapy, 8.3% in anti-CTLA-4 therapy, and 3.9% in sequential therapy of anti-PD-1 and PD-L1." (PMID 40503677, 2025). "An analysis in the field of bioinformatics discovered that, in cases of hypothyroidism resulting from CTLA-4 treatment, genes such as ALB, MAPK1, SPP1, PPARG, and MIF are found to be overexpressed." (PMID 38169638, 2024). "Hypothyroidism occurred significantly more frequently in patients receiving PD-1/PD-L1 antibody therapy compared to patients receiving CTLA4 antibodies." (PMID 38611049, 2024). "CTLA-4 inhibitors are mostly correlated with the possibility of developing hypothyroidism, while PD-1/PD-L1 inhibitors can lead to thyrotoxicosis and hypothyroidism." (PMID 38345684, 2024). "Hypothyroidism is induced by CTLA-4 inhibitors in 2.5–5.2% of the cases, by PD-1/PD-L1 inhibitors in 3.9-8.5% and by the combination of anti-CTLA-4 and anti-PD-1 in 10.2–16.4% of the patients." (PMID 38345684, 2024). "While the patient developed severe aplastic anemia, his father has psoriasis, arthritis and hypothyroidism, likely due to CTLA-4 haploinsufficiency as well." (PMID 39220156, 2024). "ICI-induced hypothyroidism is most common after CTLA-4 inhibitor/PD-1 inhibitor combination therapy, with PD-1/PD-L1 inhibitors often being the next most frequent." (PMID 37583431, 2023). "posited that pneumonia and hypothyroidism were complications more commonly observed in the context of PD-1 checkpoint blockade as compared to CTLA-4 checkpoint blockade." (PMID 36825025, 2023). "It has been reported that the incidence of irAEs with CTLA-4 inhibitors is 0-17% for hypopituitarism, 4.3-11.0% for hypothyroidism, 2.0% for hyperthyroidism, and <2% for hypoadrenocorticism." (PMID 36755909, 2023). "The estimated incidence of hypothyroidism is 2.5%-3.8% (anti-CTLA4), 3.9%-8.5% (anti-PD1/PDL1), and 10.2%-16.4% (combination therapy)." (PMID 37779728, 2023).
hypothyroidism (continued). "The overall incidence of hypothyroidism has been reported to be 6.6% and it is highest when receiving combination therapy with PD-1 plus CTLA4 inhibitors." (PMID 35360059, 2022). "Hypothyroidism is most frequent with an estimated incidence of 2.5–3.8% (anti-CTLA4), 3.9–8.5% (anti-PD1/PDL1), and 10.2–16.4% (combination treatment), typically occurring at a median time of 8–12 weeks post ICI initiation." (PMID 36149449, 2022). "Patients on anti PD-1 or PDL-1 monotherapy have higher risks of developing hypothyroidism than patients on CTLA4 inhibitors." (PMID 35360059, 2022). "Thyrotoxicosis, typically preceding hypothyroidism, has a lower incidence estimated at 0.2–5.2% (anti-CTLA4), 0.6–3.7% (anti-PD1/PDL1), and 8.0–11.1% (combination treatment)." (PMID 36149449, 2022). "With combined treatment (anti-CTLA-4 and anti-PD-1), a higher percentage of hypothyroidism was observed compared to ipilimumab (13.2% vs 3.8%)." (PMID 34236546, 2021). "Anti-CTLA-4 mAbs are connected with higher rates of hypophysitis, whereas PD-1 inhibitors more frequently induce hypothyroidism, hyperthyroidism or thyroiditis." (PMID 34483944, 2021). "Among them, hypothyroidism is mainly induced by anti-PD-1 antibody treatment, and pituitary disorder is mainly induced by anti-CTLA-4 antibody treatment." (PMID 34712202, 2021). "Taken together, across the studies depicted in these two tables, the incidence of hypothyroidism ranges from 0% to 11%) for anti-CTLA-4 mAbs, from 2.5% to 10.19% for anti-PD-1/anti-PD-L1 mAbs, and from 4% to 27% for combination regimens." (PMID 34771441, 2021). "Hypothyroidism and hyperthyroidism are reported relatively less frequently in CTLA-4 inhibitors compared with PD-1/PD-L1 inhibitors, which was consistent with the findings of a previous study." (PMID 33816235, 2021). "A total of 22 and 17 integrated human DEGs in hypothyroidism and hyperthyroidism group related to anti-CTLA-4 therapy were identified, respectively." (PMID 32500465, 2020). "This includes hypothyroidism and hyperthyroidism, especially after single CTLA-4, PD-1 blockade therapy, or the combination treatment regime." (PMID 32500465, 2020). "Among non-renal irAEs that developed during therapy with CPI (both Anti-PD-1 and Anti -CTLA-4), the most common irAE was hypothyroidism." (PMID 30612580, 2019). "Thyroid diseases and alterations (such as hypothyroidism, thyrotoxicosis, painless thyroiditis, or even thyroid storm) are reported in 1–6% of patients treated with anti–CTLA–4–antibodies, representing the second most frequent kind of irAEs." (PMID 31137683, 2019). "Among this list, only the CTLA4, PTPN22, and SH2B3 loci show significant association with hypothyroidism after correction for 107 multiple tests." (PMID 22493691, 2012). "Central hypothyroidism is observed in half of the patients treated with anti-CTLA-4 antibody, although it can be transient; therefore, our definition of hypothyroidism may have included such patients." (PMID 40503677, 2025). "The patient received a combination of ipilimumab (anti-CTLA-4) and nivolumab (anti-PD-1) complicated by hypothyroidism and elevated liver enzymes after his second dose, which was treated by levothyroxine and prednisone, followed by mycophenolate mofetil, respectively." (PMID 40181973, 2025). "The mechanisms leading to this endocrinopathy are analogous to the ones described for DM; however, both CTLA-4 and PD-1 axis blockers may lead to thyroid insufficiency." (PMID 39518461, 2024). "Additionally, anti-PD-1/PD-L1 is a more potent type of hypothyroidism-inducing ICI treatment than anti-CTLA4 and a less potent treatment than the combined type." (PMID 36188589, 2022). "In particular, a meta-analysis of 28 studies, which included more than 7,500 patients, showed an incidence of hyperthyroidism and hypothyroidism, under combined anti-CTLA4/anti-PD1 treatment, of 8% and 13.2% versus 3.2% and 3.9% in the course of an anti-PD1 treatment, respectively." (PMID 36713496, 2022).
hypothyroidism (continued). "In a case series of 10 patients with ir hypothyroidism (related to anti-PD-1 mAbs either as a monotherapy or combined with anti-CTLA-4 mAbs), thyroiditis was initially characterized by elevated anti-TgAbs in 40% of patients and elevated TRAbs in 40% of patients." (PMID 34771441, 2021). "Frequency of frank hypothyroidism is estimated to be 6.6% with ICPis, whereas the reported incidence of hyperthyroidism is lower than that of hypothyroidism (3.2% of patients treated with anti-PD-1, 0.6% with anti-PD-L1 and 1.7% with anti-CTLA-4)." (PMID 33920721, 2021). "A systematic review reported that the incidences of hypothyroidism and thyrotoxicosis were 3.8% and 1.7% after treatment with an anti-CTLA4 antibody, 7.0% and 3.2% after treatment with an anti-PD-1 antibody, and 13.2% and 8.0% after treatment with anti-CTLA4 and anti-PD-1 antibodies, respectively." (PMID 34712202, 2021). "Although hypothyroidism was reported to be more common with anti-PD-1 monotherapy and adrenal insufficiency with anti-CTLA-4 monotherapy, no such finding was observed in this study, probably because of the definition we used." (PMID 40503677, 2025). "Patients treated with anti-CTLA-4 mAbs (ipilimumab and tremelimumab) had higher risks of hypothyroidism (OR, 7.86, 95% CI, 4.10–15.04) but not hyperthyroidism (OR, 3.78, 95% CI, 0.94–15.17), compared to the control groups receiving a placebo, chemotherapy, radiation therapy, or vaccine." (PMID 34771441, 2021).